DCN (decorin)
Diseases named in the same sentence as DCN in open-access papers (continued):
Sharing a sentence is not in itself a finding about the gene and the disease.
breast carcinoma (continued). "Furthermore, it remains possible that the other variants in DCN and LUM that were not selected for genotyping in SEARCH may also influence breast cancer risk." (PMID 19036156, 2008). "Because all of these analyses were based upon RNA expression levels, we used immunohistochemical staining to assess DCN protein expression in a tissue microarray containing 65 samples of IBC and 22 of non-IBC, locally advanced primary breast cancer (LABC)." (PMID 33452400, 2021). "First, we confirmed that both proteins were expressed in the breast cancer cell lines BT-20 and T-47D; in other cell lines we examined (MCF7, MDA-MB231, and HeLa S3), periostin was present but decorin was not." (PMID 25400079, 2014). "There was also no decorin mRNA detected in the area within breast tissue specimen containing malignant proliferation of ductal or lobular epithelial cells with myoepithelium, the so-called ductal carcinoma in situ (DCIS), and lobular carcinoma in situ (LCIS) (data not shown)." (PMID 23007289, 2013).
colon carcinoma (27 papers, 2001 to 2024). "Our recent discovery that decorin deficiency promotes EMT and colon cancer metastasis is supported by the observations that exogenous decorin inhibits EMT in glioma cells as well as inflammatory breast cancer growth and metastasis." (PMID 34982945, 2022). "For example, the heparin sulfate and chondroitin sulfate levels were significantly increased in colon carcinomas, while the level of collagen-associated proteoglycan decorin decreased in some cases." (PMID 34829393, 2021). "TGF-β1 and bFGF were the strongest suppressors of decorin expression at the protein level in human colon cancer associated fibroblasts (CAFs)." (PMID 33924197, 2021). "Interestingly, E-cadherin, a protein that regulates cell-cell adhesion, epithelial-mesenchymal transition, and metastasis, was almost completely lost from the DCN KO intestine, and loss of DCN and E-cadherin accelerated colon cancer cell growth and invasion." (PMID 26697491, 2015). "Decorin was originally discovered by several laboratories and designated DSPG1 or PG40 because of its apparent molecular weight of the protein core and subsequently identified in various tissues and in the stroma of colon cancer." (PMID 35159071, 2022). "In a mice model of colon carcinoma, decorin inhibits the growth and migration of cancer cells through regulating the level of E-cadherin." (PMID 34386415, 2021). "This is in accordance with published data for both proteins in stem compartments of glioblastoma and neuroblastoma, and for DCN in colon cancer." (PMID 34253873, 2021). "DCN was proved not only contributed to colonic carcinogenesis, but also is a novel potential biomarkers for the diagnosis of colon cancer, however its function in ovarian cancer has not been investigated." (PMID 33987033, 2021). "Colon carcinoma tumor cells in vitro were able to suppress decorin production of LX2 stellate cells, a fibroblast cell line of liver origin." (PMID 32824864, 2020). "In humans, low levels of decorin in the liver facilitated the development of colon carcinoma metastases in proportion with more aggressive phenotypes, indicating a possible antitumor action of the proteoglycan." (PMID 32824864, 2020). "Human CRC tissues lack decorin expression in vivo and in vitro, and adenovirus-mediated transduction of decorin into human colon cancer cell lines significantly reduces their colony-forming ability." (PMID 32824864, 2020). "In the stroma of primary colon tumors, while decorin was still abundant, its expression was reduced compared to the normal tissue." (PMID 32824864, 2020). "The low expression of decorin (DCN) has been demonstrated to contribute to be as a potential biomarker in colon cancer." (PMID 32714651, 2020). "The same trend was observed in this study as well wherein the expression of Decorin was 2-fold down-regulated in colon tumor tissues." (PMID 29568375, 2018). "A large number of studies are focussing on considering Decorin as a molecule of high therapeutic potential in case of colon cancer." (PMID 29568375, 2018). "In this study, we identified expression of 13 potential miRNAs and mRNA regulatory pairs, among which, notably, mir-200c and DCN have been previously reported in colon cancer." (PMID 28567416, 2017). "Furthermore, it has been shown that ectopic expression of DCN in a variety of cells such as glioma cells, colon cancer cells and inflammatory breast cancer cells inhibited the growth and the invasive capacities of these tumor cells." (PMID 38667295, 2024). "In addition, safety evaluations showed no observed cardiotoxicity or hepatotoxicity in the combination therapy group, indicating the safety and efficacy of NK cells combined with rAd.DCN in the treatment of colon cancer." (PMID 39482550, 2024). "Based on this, we set out to investigate whether excess decorin may protect against the liver metastases of colon carcinoma." (PMID 32824864, 2020).
colon carcinoma (continued). "We first determined changes in the level of decorin in the liver metastases of human colon carcinoma and examined whether the tumor cells may directly influence the production of decorin by myofibroblasts." (PMID 32824864, 2020). "Based on these results, we designed a new set of experiments to investigate whether decorin also protects against liver metastases of colon carcinoma." (PMID 32824864, 2020). "We also analyzed the effect of decorin in tissue microarrays of human colon carcinoma liver metastasis and examined whether the tumor cells can directly influence the decorin production of myofibroblasts." (PMID 32824864, 2020). "In vitro, colon carcinoma cells inhibited decorin expression in LX2 hepatic stellate cells." (PMID 32824864, 2020). "DCN was also seen to be potential biomarker of Colon Cancer." (PMID 32489319, 2020). "As fibroblasts are the main producers of decorin, we tested whether colon cancer cells can influence decorin expression of liver fibroblast cells in a model that mimicked tumor cell invasion to the liver." (PMID 32824864, 2020). "Moreover, liver-targeted decorin delivery effectively inhibited metastasis formation of colon cancer." (PMID 32824864, 2020). "Moreover, liver-targeted decorin delivery in mice effectively attenuated metastasis formation of colon cancer." (PMID 32824864, 2020). "Interestingly, it is reported that decorin inhibits the growth of colon carcinoma cells by the upregulation of p21." (PMID 30813947, 2019). "Decorin is known to be a tumor suppressing gene involved in colon cancer and metastasis." (PMID 29568375, 2018). "The theory discussed here may be applied to other tumor types, as similar DCN expression profiles were found also in colon cancers 44, where increased DCN correlated with suppressed tumor growth." (PMID 27398310, 2016). "Because methylation of the decorin gene has previously been shown to regulate decorin expression in colon cancer, we decided to examine whether this epigenetic mechanism is affecting decorin expression in human bladder cancer cells as well." (PMID 24146840, 2013). "Furthermore, in decorin knockout mice, colon cancer xenografts exhibited greater tumor weight and reduced E-cadherin expression in intestinal epithelial cells, whereas increasing decorin expression in colon cancer cells concomitantly upregulated E-cadherin expression." (PMID 38928185, 2024). "The fibroblasts and myofibroblasts were visualized by anti-human RGS5, decorin, podoplanin/gp36, CD36, α-SMA, and HHIP antibodies in colon mucosa and colon cancer tissues." (PMID 36463319, 2022). "We identified 7 known genes (focal adhesion kinase, deleted in colon cancer, guanine binding inhibitory protein α, glutamine synthetase, ornithine aminotransferase, M130, and pepsinogen C) and 2 previously unknown genes as being overexpressed in HCC, and 1 gene (decorin) as suppressed in HCC." (PMID 11461082, 2001). "Since DCN was identified dominantly to be expressing in OGN+ fibroblasts, consistently, DCN staining was also dramatically decreased and did not encircle any cancer cells in colon cancer tissues." (PMID 36463319, 2022).
glioma (26 papers, 2007 to 2025). A benign or malignant brain and spinal cord tumor that arises from glial cells (astrocytes, oligodendrocytes, ependymal cells). "Reduced expression of decorin in glioma tissues was associated with a poor survival of the patients." (PMID 34386415, 2021). "The mechanisms underlying the up‐regulation of decorin in glioma needs further investigation." (PMID 27398310, 2016). "Inhibition of experimental rat glioma growth by decorin (TGFβ antagonism) gene transfer was associated with decreased microglia infiltration suggesting that the GAMs were participate in the regression of decorin-expressing rat C6 gliomas." (PMID 23983766, 2013). "The mechanism underlying the autophagy induction by DCN in glioma cells was still unknown." (PMID 27398310, 2016). "In mouse and rat models of glioma, decorin was shown to inhibit tumor growth by regulating the immune response mediated by T cells and microglia." (PMID 38805346, 2024). "While mutations in EFEMP2, ADAM10, SERPINH1, ADAM15, GAS6 and TNXB were detected only in patients with glioma grade 3, mutations in LTBP2, DCN, CRELD1 and HAPLN3 were observed only in patients with glioma grade 4, GBM." (PMID 38272115, 2024). "In glioma, decorin mostly acts as a suppressor of cancer metastasis by modulating signal transduction in pathways such as c-Met/Akt/mTOR to disrupt EMT." (PMID 37013486, 2023). "The roles of DCN in mitophagy and autophagy have been determined in triple-negative breast carcinoma 59, endothelial 60, and glioma cells." (PMID 36438479, 2022). "Collectively, these findings suggest that decorin inhibits EMT phenotype through the induction of autophagy in glioma cell lines." (PMID 34386415, 2021). "In U87MG glioma cells, decorin-mediated inhibition of cell migration involved the activation of autophagy and suppression of TGF-β signaling." (PMID 34021540, 2021). "We found a higher decorin expression level in normal astrocyte cell line while at low levels in all glioma cells studied." (PMID 34386415, 2021). "Curiously, as observed in several types of non-central nervous system tumors, soluble DCN potently induces autophagy in GBM cells and contributes to an impairment of GBM cell migration in vitro experiments." (PMID 34178638, 2021). "Unlike our previous study showing syndecan 1 to be the main VAR2CSA receptor in the placental syncytium, we found several interesting hits on the glioma cell lines, including syndicans, glypicans, neuropilins, decorin, versican, CSPG4, and PTPRZ1." (PMID 31466397, 2019). "We found that soluble decorin protein core potently induced autophagy in U87MG glioma cells, as evidenced by both the accumulation of LC3 and the degradation of p62." (PMID 27398310, 2016). "Although possible inhibition of DCN on cell migration and invasion has been implied in glioma 25, 26, the precise function and the possible mechanisms has not yet been elucidated." (PMID 27398310, 2016). "We further confirm the suppressive effect of DCN on glioma cell migration by knocking down the expression of endogenous DCN with siRNA." (PMID 27398310, 2016). "Taken together, these data suggested that DCN inhibition on glioma migration and TGF‐β signaling were closely related or probably through autophagy to mediate the effect of TMZ." (PMID 27398310, 2016). "In conclusion, we discovered that decorin exhibited an antimigration effect in U87MG glioma cells with the induction of autophagy and consequent inhibition of TGF‐β signaling." (PMID 27398310, 2016). "Transfection of siRNA targeting DCN attenuated the suppressive effect of TMZ on glioma cell migration and adhesion." (PMID 27398310, 2016). "This indicated that DCN‐induced autophagy in glioma cells was canonically dependent on class III phosphoinositide 3‐kinase." (PMID 27398310, 2016). "Our results indicated that the migration of glioma cells was under the control of the active status of autophagy, with DCN serving as a key player, as well as an indicator of the outcome." (PMID 27398310, 2016).
glioma (continued). "We found that both addition of DCN protein core or overexpressed DCN was able to drastically suppress the migration of glioma cells." (PMID 27398310, 2016). "We selectively examined the cerebro‐spinal fluid (CSF) level of DCN from glioma patients or other non‐neoplastic disorders with pooled samples, the results seemed in support of the conclusion from microarray analyses." (PMID 27398310, 2016). "We found that either soluble DCN protein core or overexpression of DCN exhibited a potent antimigration effect in glioma cells." (PMID 27398310, 2016). "Nonetheless, the exact role of DCN‐induced autophagy for the suppression of tumor cells demands further investigation, especially in specific invasive cancers like glioma." (PMID 27398310, 2016). "In contrast, DCN has been reported to play protective and antiapoptotic roles in glioma cell lines exposed to hypoxic microenvironments." (PMID 26230845, 2015). "To test the possibility of glioma gene therapy using AAV vector expressing decorin, we performed both in vivo and in vitro experiments, inhibiting human glioma growth in the brain of nude mice and proteomic analysis on cultured U87MG glioblastoma cells." (PMID 24625664, 2014). "DCN (decorin) was known as tumor suppressor in glioma but it was found to be up regulated in our patient cohort as well as in GSE1993, GSE4422 and TCGA datasets." (PMID 24475040, 2014). "Intracranial injection of AAV-decorin vector to the glioma-bearing nude mice in vivo significantly suppressed brain tumor growth and prolonged survival when compared to control non-treated mice bearing the same U87MG tumors." (PMID 24625664, 2014). "Our proteomics data suggest that dsAAV-decorin induces differentiation of glioma cells by evoking multiple biochemical mechanisms that render human glioma cells vulnerable to chemical or radiation therapies." (PMID 24625664, 2014). "Proteomics analysis on protein expression profiles in the U87MG glioma cells after AAV-mediated decorin gene transfer revealed up- and down-regulation of important proteins." (PMID 24625664, 2014). "In this study, we investigated the therapeutic effect of an anti-cancer protein, decorin, by delivering it into a xenograft U87MG glioma tumor in the brain of nude mice through an adeno-associated viral (AAV2) gene delivery system." (PMID 24625664, 2014). "As an example of glioma therapy using ECM protein, decorin, which is poorly expressed by glioma cell lines, was ectopically expressed in glioma cells and successfully used to abrogate the growth of experimental gliomas." (PMID 17578585, 2007). "Several ECM components and their fragments, such as decorin and endostatin are being tried as potential targets for glioma gene therapy." (PMID 17578585, 2007). "Previous studies found that DCN could activate autophagy in different kinds of cells including glioma, human hepatoma HepG2, endothelial, and nucleus pulposus cells." (PMID 35391926, 2022). "Notably, these initial observations of decorin-evoked autophagic flux have been recently confirmed in other systems including intervertebral disc cells, trophoblasts and glioma cells." (PMID 34982945, 2022). "In situ hybridization (ISH) has localized decorin in areas of microvascular proliferation within gliomas and may be a therapeutic target in anti-angiogenic therapy or approaches targeting TGF-β activity in tumors." (PMID 34409033, 2021). "The fact that DCN expression could be boosted by TMZ treatments implied a sophisticated DCN‐mediated outcome for glioma metastasis in real patients undergoing chemotherapies." (PMID 27398310, 2016). "An increased level of DCN in glioma patients was found as compared with paracancerous tissues." (PMID 27398310, 2016). "We further investigated if DCN is able to activate autophagy in glioma cells." (PMID 27398310, 2016).
glioma (continued). "On the contrary, as U87MG cells transfected with increasing doses of DCN siRNA, the conversion of LC3 I to LC3 II decreased, p62/SQSTM1 levels increased, suggesting that DCN may function in maintaining the basal autophagy level in glioma cells." (PMID 27398310, 2016). "Overexpression of DCN was indicated to suppress glioma cell growth." (PMID 27398310, 2016). "In this study, the effect of DCN on the migration of glioma cells was investigated." (PMID 27398310, 2016). "DCN also enhances the evasion of the immune system and muscle invasion in prostate cancer in vivo, and exerts unexpected protective and antiapoptotic effects in glioma cell lines under hypoxic conditions." (PMID 26230845, 2015). "Previous studies have shown that DCN inhibits glioma growth and cell differentiation." (PMID 26230845, 2015). "However, the effects of decorin expression on glioma cells, including cell differentiation and proliferation have not been examined." (PMID 24625664, 2014). "Decorin directly binds and activates EGFR as an EGFR ligand and causes a down-regulation of EGFR and its signaling, leading to a growth inhibition and cell differentiation in certain non-glioma cancer cells." (PMID 24625664, 2014). "Also, DCN knockout significantly induced cell invasion in glioma cell lines." (PMID 38667295, 2024). "Thus, we sought to examine whether c-Met/PI3K/Akt axis is involved in decorin-induced EMT inhibition in glioma cells." (PMID 34386415, 2021). "However, the role of DCN in the migration of glioma cells remain elusive." (PMID 27398310, 2016). "In conclusion, decorin suppresses invasion and EMT phenotype of glioma by inducing autophagy via c-Met/Akt/mTOR axis." (PMID 34386415, 2021). "In conclusion, this study provides evidence that overexpressed decorin attenuated the EMT, migration and invasion of human glioma cells." (PMID 34386415, 2021). "Decorin overexpression suppressed cell migration, invasion and attenuated EMT phenotype in glioma cell lines." (PMID 34386415, 2021). "An immediate possible explanation would be that DCN was a required player in TMZ‐induced autophagy, which in turn suppressed the glioma cell migration through TGF‐β signaling." (PMID 27398310, 2016). "To evaluate the role of autophagy in DCN‐induced migration inhibition and TGF‐β suppression in glioma cells, we treated U87MG cells with 3‐MA for ECIS assays." (PMID 27398310, 2016). "In this study, we found that treatment with exogenous DCN inhibited the adhesion and migration of U87MG glioma cells with down‐regulation of TGF‐β signaling." (PMID 27398310, 2016). "Additionally, Decorin (DCN), which plays a role in collagen fibril assembly, and Tenascin-C (TNC), commonly expressed in gliomas, were also downregulated." (PMID 40813676, 2025). "Although decorin has been shown to induce p21 expression and cell cycle arrest in some cancers, this effect is not observed in glioma cells, indicating that perhaps gliomas have diverse TGF-β signaling relative to other cancers." (PMID 38926762, 2024). "We further assessed the decorin expression using Western blot on different GBM cells including normal human astrocyte cell line (NHAs), established (U87MG, T98G, U251, A172 and U118) and primary glioma cell lines (P017, P025 and P035)." (PMID 34386415, 2021). "Decorin or NFκB inhibitor treatment of Nf1OPG mice at 4–6 WOA inhibits tumor formation at 12 WOA, thus establishing a potential mechanistic etiology for the attenuated glioma incidence observed in children with asthma." (PMID 34880260, 2021). "Decorin protects neuronal tissue from the damaging effects of anti-oxidants and neuroinflammation following TBI by inactivation and has anti-tumor activity by inhibiting glioma cell migration." (PMID 34409033, 2021). "Because a low expression of decorin was correlated with a poor prognosis in patients with GBM, we then investigated whether decorin played a functional role in glioma cells." (PMID 34386415, 2021).